AUTS2 (activator of transcription and developmental regulator AUTS2)
Diseases named in the same sentence as AUTS2 in open-access papers (continued):
Sharing a sentence is not in itself a finding about the gene and the disease.
Sepsis (1 paper, 2023). Sepsis is defined as life-threatening organ dysfunction caused by a dysregulated host response to infection. "S1PR5, GNLY, CD247, KLRG1, IL-1R2, AUTS2, IL-2Rβ, ARG1, TGFBR3, TLR5 and PRF1 in the top 80 genes in the two modules were located toward the center of the co-expression network, and CD247, IL-2Rβ, TGF-βR3 and IL-1R2 were identified as core genes in sepsis." (PMID 36855106, 2023).
T-cell leukemia (1 paper, 2016). A malignant disease of the T-lymphocytes in the bone marrow, thymus, and/or blood. "Therefore, we asked if STAG3L4 and/or AUTS2 show aberrant expression patterns in T-cell leukemia." (PMID 27322685, 2016).
T-cell lymphoma (1 paper, 2019). "RQ-PCR analysis of AUTS2 in T-cell lymphoma cell lines and primary hematopoietic cells showed enhanced expression in DERL-2/7." (PMID 31143370, 2019).
neurological disorders (26 papers, 2013 to 2025). "Further examination using our Auts2 cKO mice will help to understand the pathological insights into the neurological disorders caused by AUTS2 mutations." (PMID 33305180, 2020). "The human AUTS2 locus is associated with a wide diversity of neurological disorders, indicating that AUTS2 is involved in neurodevelopment (see Hori & Hoshino, 2017 for review)." (PMID 30723624, 2019). "They found that AUTS2 interacts with the promoters/enhancers of various genes that are related to brain development and also associated with neurological disorders." (PMID 28505103, 2017). "Our enhancer results, combined with the observation that human-specific neurological disorders are associated with mutations in this gene, suggest that AUTS2 has an important role in the evolution of human cognitive traits." (PMID 23349641, 2013). "AUTS2, mainly expressed in the brain, is linked to various neurological diseases." (PMID 38274809, 2023). "The AUTS2 gene is associated with multiple neurodevelopmental disorders and neurological disorders." (PMID 36895015, 2023). "In addition, the genomic structural variants in the AUTS2 locus have been associated with multiple types of neurological disorders such as attention deficit hyperactivity disorder (ADHD) and dyslexia." (PMID 33305180, 2020). "In contrast, AUTS2 is frequently disrupted in patients with neurological disorders but is less studied in cancer." (PMID 37679762, 2023). "AUTS2 is also involved in neurodevelopment and is identified as a candidate gene for numerous neurological disorders." (PMID 38136943, 2023). "Genetic alterations in the 5′ end of AUTS2 locus are related to numerous neurological disorders including ASD, ADHD, micro- and macrocephaly, intellectual disability, mental retardation or alcohol consumption." (PMID 36479251, 2022). "Data in mouse and zebrafish indicate that Auts2 acts as a transcriptional regulator for neural development through interactions with several genes related to brain development and neurological disorders." (PMID 30723624, 2019). "MBD5, OGDHL, AUTS2, EGR3, QPCT, and ITGA8 are linked to neurological diseases." (PMID 39588153, 2024). "It is important to stress that genetic alterations in the 3′ of AUTS2, with a yet unknown relevance from the evolutionary standpoint, are also related to neurological disorders and seem more penetrant than alterations in the 5’ end of the gene." (PMID 36479251, 2022). "In addition to AUTS2's role in neurological disease, it was also shown to be important for human-specific evolution." (PMID 23349641, 2013). "Combined, our results show that AUTS2 is important for neurodevelopment and expose candidate enhancer sequences in which nucleotide variation could lead to neurological disease and human-specific traits." (PMID 23349641, 2013). "Similarly, the effects of AUTS2 on Drosophila EGFR signalling are compatible with a role for this protein in the regulation of Erk activity in humans, and that this effects might underline the effects of zebrafish, murine and human mutations in the onset of neurological disorders." (PMID 24348264, 2013).
neurodevelopmental disorder (22 papers, 2010 to 2025). A behavioral and cognitive disorder with onset during the developmental period that involves impaired or aberrant development of intellectual, motor, or social functions. "Here, we use the medaka, a model fish species, to investigate the role of auts2a, the ortholog of human AUTS2, a gene repressed in the fish oocyte following maternal stress and associated with neurodevelopmental disorders." (PMID 40346605, 2025). "We focused on auts2a (i.e., the ortholog of AUTS2), a gene maternally repressed in the fish oocyte following maternal stress and associated with neurodevelopmental disorders (NDDs), including autism spectrum disorders (ASD)." (PMID 40346605, 2025). "A second ncPRC1 subunit implicated in neurodevelopmental disorders is autism susceptibility candidate 2 (AUTS2)." (PMID 36547251, 2022). "AUTS2 was originally linked to neurodevelopmental disorders in a study that described a pathogenic mutation found in a pair of monozygotic twins with ASD." (PMID 36547251, 2022). "Taken together, a comprehensive understanding of Auts2 functions can give deep insights into the cause of the heterogenous manifestation of neurodevelopmental disorders such as ASD." (PMID 33967843, 2021). "The AUTS2 gene is a novel gene that is initially linked to neurodevelopmental disorders in a pair of autistic monozygotic twin sisters." (PMID 25347278, 2014). "Finally, we report that auts2a/AUTS2 is part of a group of evolutionarily conserved genes associated with human neurodevelopmental disorders and expressed in oocytes across species, from fish to mammals." (PMID 40346605, 2025). "FMRP translational activation of large proteins may be critical for normal human development, as more than 20 FMRP targets including Auts2 are dosage sensitive and are associated with neurodevelopmental disorders caused by haploinsufficiency." (PMID 35731217, 2022). "Thus, the complexity of phenotypes caused by Auts2 mutations or genetic variations are consistent with the broad range of symptoms manifested by neurodevelopmental disorders, indicating its comprehensive roles in the development of brain functions." (PMID 33967843, 2021). "The autism susceptibility candidate 2 (AUTS2; also known as activator of transcription and developmental regulator) gene is a known regulator of transcription in the nervous system and is associated with several neurodevelopmental disorders including ASD." (PMID 34544758, 2021). "Mutations of AUTS2 have been correlated with neurodevelopmental disorders." (PMID 27322685, 2016). "As Auts2 function in neurodevelopmental disorders has been addressed in a number of comprehensive reviews, we will here only briefly discuss its role in mouse and zebrafish development." (PMID 34805182, 2021). "A detailed mapping of Auts2 function in a circuit-specific manner would greatly increase our knowledge for the behavioral abnormalities of neurodevelopmental disorders, and maybe lead to a novel treatment strategy." (PMID 33967843, 2021). "Moreover, chromosomal rearrangements of AUTS2 have been described in neurodevelopmental disorders and B-cell precursor ALL." (PMID 27322685, 2016). "Likewise, the transcriptional activator AUTS2, KCNH7 potassium channel variants, lysine methyltransferase SETD2 (which is also downregulated in mice), and USP7, among others, are induced by rest, and their mutations are associated with a variety of neurodevelopmental disorders." (PMID 40725218, 2025). "Moreover, genomic deletions of 5’-exons have been described in patients with neurodevelopmental disorders, and an aberrant gene fusion of 5’-PAX5 and 3’-AUTS2 in B-ALL patients results in losses of anterior parts of AUTS2 protein." (PMID 28977998, 2017). "Genomic aberrations targeting AUTS2 have been reported in patients with neurodevelopmental disorders and B-cell precursor ALL while absent from T-ALL as shown here." (PMID 27322685, 2016).
cancer (16 papers, 2017 to 2025). A tumor composed of atypical neoplastic, often pleomorphic cells that invade other tissues. "Pan-cancer single nucleotide variation analysis showed that the overall average mutation frequency ranged from 0 to 8.2%, and CRGs including AUTS2, TIMELESS, REV1, and PER2 showed high mutation frequencies." (PMID 36895015, 2023). "Most reports studying MAPT (microtubule-associated protein tau) and AUTS2 (autism susceptibility gene 2 protein) have focused on neural diseases and only a few studies have investigated their functions in cancer progression." (PMID 29215599, 2017). "In addition, AUTS2 was also reported to be positively associated with other cancer progression via TGF-beta pathway activation, HEDGEHOG and WNT signaling pathway." (PMID 37733241, 2023). "We also observed upregulation of AUTS2 and TXK in liver NK cells, both of which been associated with poor prognosis and malignant progression in multiple human cancers." (PMID 40443661, 2025). "These genes were presumably involved in cancer (SMG6, HCK), cellular growth (CPVL), reproduction (ADGB, CRISP1, CTTNBP2NL, WDR78), and nervous system (AUTS2, CNTNAP2, CPVL, SRGAP2)." (PMID 40149444, 2025).
tumor (10 papers, 2017 to 2024). "We identified its downstream effector genes, EMP1 and AUTS2, which play crucial roles in mediating its tumor-suppressing effects." (PMID 37679762, 2023). "We found that the expression levels of two upregulated genes (L1CAM and FBN1) were also increased along with tumor grade and that the expression levels of four downregulated genes (AUTS2, MAPT, AGT and USH1C) were decreased along with tumor grade." (PMID 29215599, 2017). "With regards to the clinical analysis of ccRCC samples from microarrays of GSE66272 and GSE73731, the upregulation of L1CAM and FBN1 and downregulation of AUTS2, MAPT, AGT and USH1C were observed along with an increase in tumor grade." (PMID 29215599, 2017). "However, our findings suggest the potential tumor suppression function of MAPT and AUTS2 in the progression of ccRCC." (PMID 29215599, 2017). "Furthermore, AUTS2 and PCGF5 may (de)regulate ONECUT2 activity via chromatin modifications in the tumor cells." (PMID 38474011, 2024).
psychiatric disorder (6 papers, 2015 to 2022). A disorder characterized by behavioral and/or psychological abnormalities, often accompanied by physical symptoms. "Because vocal communication deficits were also observed in heterozygous Auts2 cKO mice, this study should provide insight into understanding the pathology of human psychiatric disorders with AUTS2 mutations, which are in general, heterozygous." (PMID 33305180, 2020). "Comparative analyses of the different forms of Auts2 mouse mutants will help us to better understand the pathological mechanisms of the psychiatric disorders caused by AUTS2 mutations." (PMID 32498016, 2020). "Recently, a key gene for various psychiatric diseases, the Autism susceptibility candidate 2 (AUTS2), has been shown to regulate neuronal migration, which gives new insight into understanding this question." (PMID 28505103, 2017). "Together, these findings suggest that AUTS2 regulates excitatory synapse number to coordinate E/I balance in the brain, whose impairment may underlie the pathology of psychiatric disorders in individuals with AUTS2 mutations." (PMID 32498016, 2020). "We believe that investigation of the Autism susceptibility candidate 2 (AUTS2) gene may shed insight on this question, as this gene is related to various psychiatric diseases and also known to be involved in neuronal migration." (PMID 28505103, 2017). "Moreover, the extent of AUTS2 contribution to the pathogenesis of psychiatric disorders associated with the cerebellum remains unclear." (PMID 33305180, 2020).
digestive system diseases (1 paper, 2024). "AUTS2 is associated with digestive system diseases, affecting the feed efficiency of cattle and thus growth speed." (PMID 39119576, 2024).
AUTS2 also shares sentences with these, for which no sentence is quoted: attention deficit-hyperactivity disorder (6 papers); alcoholism (3); depression (3); cognitive disorder (2); diabetes (2); heroin addicts (2); intellectual disability syndrome (2); lung adenocarcinoma (2); lung carcinoma (2); Visual impairment (2); alcohol addiction (1); Alzheimer disease (1); astrocytoma (1); autoimmune disease (1); Autoimmunity (1); autosomal dominant intellectual disability syndrome (1); bipolar disorder (1); brain disease (1); central nervous systemic disorders (1); cerebral palsy (1); colorectal cancer (1); communication disorder (1); Cri-du-chat syndrome (1); deafness (1); glaucoma (1); Hirschsprung disease (1); KBG syndrome (1); language disorder (1); lung (1); lymphoma (1).
A further 14 diseases each share a sentence with AUTS2 in 1 paper.